GPANK1 (G-patch domain and ankyrin repeats 1)
Synonyms: ANKRD59; BAT4; G5; GPATCH10; D6S54E
Tractability: PROTAC: UniProt records ubiquitination sites on it; ubiquitination databases record sites on it.
Gene: Protein-coding gene on chromosome 6 (31,661,228 to 31,666,283, reverse strand). Ensembl gene ENSG00000204438.
Subcellular location (Human Protein Atlas): Endoplasmic reticulum
Gene Ontology:
Molecular function: protein binding; nucleic acid binding
Genetic constraint (gnomAD): Loss-of-function variants: 23 observed, 27.66 expected, observed/expected ratio (o/e) 0.83, 90% interval 0.6 to 1.18. The upper end of that interval is the gene's LOEUF score, 1.18, which puts it in group 5 of 6, group 1 being the genes least tolerant of losing a copy. Missense variants: 466 observed, 469.68 expected, observed/expected ratio (o/e) 0.99, 90% interval 0.92 to 1.07. Synonymous variants: 174 observed, 186.71 expected, observed/expected ratio (o/e) 0.93, 90% interval 0.82 to 1.06.
Homologues: Orthologues: chimpanzee GPANK1 (99% identical), macaque GPANK1 (95% identical), dog GPANK1 (84% identical), rabbit GPANK1 (82% identical), pig GPANK1 (82% identical), rat Gpank1 (79% identical), mouse Gpank1 (79% identical), guinea pig GPANK1 (76% identical), tropical clawed frog gpank1 (37% identical), Drosophila melanogaster CG8152 (26% identical), Caenorhabditis elegans ZK1320.7 (22% identical), zebrafish gpank1 (17% identical).
Diseases named in the same sentence as GPANK1 in open-access papers:
GPANK1 is named in the same sentence as 7 diseases in open-access papers, as found by Europe PMC text mining. Sharing a sentence is not in itself a finding about the gene and the disease. The quoted sentences say what the papers report.
celiac disease (1 paper, 2017). An autoimmune genetic disorder with an unknown pattern of inheritance that primarily affects the digestive tract. "The strongest independent CD interaction signal corresponded to genes in the HLA class III region, in particular PRRC2A and GPANK1/C6orf47, which are known to contain variants for non-Hodgkin's lymphoma and early menopause, co-morbidities of celiac disease." (PMID 28282431, 2017).
epilepsy (1 paper, 2026). A brain disorder characterized by episodes of abnormally increased neuronal discharge resulting in transient episodes of sensory or motor neurological dysfunction, or psychic dysfunction. "PCR results show the expression of IER3, TNF, GPANK1, and ATF6B in hippocampus of epilepsy model largely consistent with bioinformatics predictions." (PMID 41466027, 2026). "The differential expression of four DE‐SRGs between control and epilepsy groups, including IER3, TNF, GPANK1 (upregulated), and ATF6B (downregulated), further elucidates the molecular mechanisms underlying the epilepsy phenotype." (PMID 41466027, 2026). "Finally, the expression of four key genes (IER3, TNF, GPANK1, and ATF6B) in the hippocampus of epilepsy mouse model was quantified using PCR." (PMID 41466027, 2026). "Finally, although we validated the altered expression of IER3, TNF, GPANK1, and ATF6B in multiple epilepsy models, we did not investigate the correlation between their expression levels and behavioral seizure outcomes (e.g., Racine scores, seizure frequency)." (PMID 41466027, 2026).
osteosarcoma (1 paper, 2023). A usually aggressive malignant bone-forming mesenchymal neoplasm, predominantly affecting adolescents and young adults. "However, recurrent gene fusions in pediatric cancers rarely involve these regions, with only two cases validated in 48 tumors from the MOSCATO-01 cohort (two translocations t and generating GPANK1::ABHD16A and PPP1R18::FXR2 gene fusions in eRMS and osteosarcoma cases, respectively)." (PMID 38318504, 2023).
GPANK1 also shares sentences with these, for which no sentence is quoted: cancer (2 papers); autosomal recessive spastic paraplegia-86 (1); non-Hodgkin lymphoma (1); Spastic paraplegia (1).